PLAAT1 (phospholipase A and acyltransferase 1)
Description:
Exhibits both phospholipase A1/2 and acyltransferase activities. Shows phospholipase A1 (PLA1) and A2 (PLA2) activity, catalyzing the calcium-independent release of fatty acids from the sn-1 or sn-2 position of glycerophospholipids. Shows O-acyltransferase activity, catalyzing the transfer of a fatty acyl group from glycerophospholipid to the hydroxyl group of lysophospholipid. Shows N-acyltransferase activity, catalyzing the calcium-independent transfer of a fatty acyl group at the sn-1 position of phosphatidylcholine (PC) and other glycerophospholipids to the primary amine of phosphatidylethanolamine (PE), forming N-acylphosphatidylethanolamine (NAPE) which serves as precursor for N-acylethanolamines (NAEs).
Synonyms: HRSL1; HRASLS; H-REV107; HRASLS1; A-C1; PLA/AT1; PLAAT-1; HSD28
Tractability: Antibody: UniProt predicts a signal peptide or a membrane-spanning region.
Gene: Protein-coding gene on chromosome 3 (193,240,620 to 193,277,738, forward strand). Ensembl gene ENSG00000127252.
Subcellular location: Membrane (Isoform 1); Cytoplasm; Nucleus (Isoform 2)
Subcellular location (Human Protein Atlas): Focal adhesion sites; Cytosol
Pathways (Reactome):
Metabolism: Acyl chain remodelling of PE
Gene Ontology:
Molecular function: acyltransferase activity, transferring groups other than amino-acyl groups; phospholipase A1 activity; phospholipase A2 activity; protein binding; phospholipase activity
Biological process: N-acylphosphatidylethanolamine metabolic process; phosphatidylcholine metabolic process; lens fiber cell differentiation; organelle disassembly
Cellular component: cytoplasm; nucleus; cytosol; endoplasmic reticulum; lysosome; mitochondrion; nuclear envelope lumen; membrane
Genetic constraint (gnomAD): Loss-of-function variants: 13 observed, 16.88 expected, observed/expected ratio (o/e) 0.77, 90% interval 0.5 to 1.22. The upper end of that interval is the gene's LOEUF score, 1.22, which puts it in group 5 of 6, group 1 being the genes least tolerant of losing a copy. Missense variants: 218 observed, 217.62 expected, observed/expected ratio (o/e) 1, 90% interval 0.9 to 1.12. Synonymous variants: 73 observed, 82.32 expected, observed/expected ratio (o/e) 0.89, 90% interval 0.73 to 1.08.
Homologues: Orthologues: chimpanzee PLAAT1 (100% identical), macaque PLAAT1 (97% identical), pig PLAAT1 (86% identical), dog PLAAT1 (85% identical), mouse Plaat1 (84% identical), guinea pig PLAAT1 (83% identical), rat Plaat1 (83% identical), tropical clawed frog plaat1 (67% identical), zebrafish plaat1 (62% identical), zebrafish plaat1l (30% identical). Paralogues in human: PLAAT3 (45% identical), PLAAT2 (42% identical), PLAAT4 (42% identical), PLAAT5 (35% identical), LRAT (28% identical), LRATD2 (23% identical), LRATD1 (20% identical).
Diseases named in the same sentence as PLAAT1 in open-access papers:
PLAAT1 is named in the same sentence as 15 diseases in open-access papers, as found by Europe PMC text mining. Sharing a sentence is not in itself a finding about the gene and the disease. The quoted sentences say what the papers report.
endometrial carcinoma (1 paper, 2025). A malignant tumor arising from the epithelium that lines the cavity of the uterine body. "First, we found that PLAAT1 was ubiquitously expressed in the four endometrial carcinoma cell lines at both the mRNA and protein levels." (PMID 40988925, 2025). "Our research also indicates that PLAAT1 plays an oncogenic role in endometrial cancer, as its knockdown suppressed the proliferative, migratory, and invasive capacity of endometrial cancer cells." (PMID 40988925, 2025). "To investigate the function of PLAAT1 in endometrial cancer cells, we downregulated its expression in HEC-1A cells through siRNA (p < 0.05)." (PMID 40988925, 2025). "Our findings highlight the oncogenic potential of PLAAT1 in endometrial cancer and provide novel insights into the diagnosis and therapy of this cancer type." (PMID 40988925, 2025). "Given that we identified a strong association between PLAAT1 and CD8+ T-cell infiltration, we then used in vitro experiments to clarify the impact of PLAAT1 on the biological behaviour of endometrial cancer cells." (PMID 40988925, 2025). "Cytological experiments confirmed that the knockdown of PLAAT1 effectively suppressed the proliferation and motility of endometrial cancer cells." (PMID 40988925, 2025). "Finally, the molecular mechanisms underlying the effects of one of our identified potential targets, PLAAT1, on the proliferation and invasion of endometrial cancer cells require further elucidation." (PMID 40988925, 2025). "In conclusion, our data suggested that PLAAT1 may play a carcinogenic role in endometrial cancer." (PMID 40988925, 2025).
Obesity (1 paper, 2025). Accumulation of substantial excess body fat. "Deficiency in PLAAT1 and 3 causes resistance to HFD-induced obesity with distinct effects on the liver and WAT." (PMID 40244184, 2025).
viral infection (1 paper, 2022). "Our study provides novel insights into the functions of PLAAT1 in host immune response to viral infection." (PMID 36172355, 2022). "In this study, we investigated the functions of PLAAT1 in host immune responses to viral infection in zebrafish." (PMID 36172355, 2022).
tumor (8 papers, 2014 to 2024). "PLAAT1 (HRASLS) regulated cell proliferation, tumor suppression, and phospholipid metabolism." (PMID 38363409, 2024). "PLAAT1 is a member of the PLAAT protein family and plays important roles in tumor suppression, transglutaminase activation and peroxisomal biogenesis." (PMID 36172355, 2022). "PTGIS and PLAAT1 might serve as new therapeutic targets for LUSC as well as biomarkers for prognosis and tumor immunity." (PMID 38363409, 2024).
cancer (5 papers, 2013 to 2025). A tumor composed of atypical neoplastic, often pleomorphic cells that invade other tissues. "Among these model genes (FLNC, KLK6, PTGIS, PLAAT1 and GLYATL2), FLNC is an actin-binding protein that regulates the actin cytoskeleton in cells and is involved in cancer metastasis." (PMID 38363409, 2024). "Many of the genes such as JHY, PLAAT1, PNMA8B, RPL37P6, SNX32, UGGT2 and Y_RNA have not been related to any cancer, yet." (PMID 33672117, 2021).
infection (2 papers, 2019 to 2022). The state of being infected such as from the introduction of a foreign agent such as serum, vaccine, antigenic substance or organism. "Interestingly, SVCV infection resulted in aggregation of PLAAT1 in the cytoplasm." (PMID 36172355, 2022). "PLAAT1 colocalized with IRF3 and IRF7 without or with SVCV infection." (PMID 36172355, 2022).
PLAAT1 also shares sentences with these, for which no sentence is quoted: adenocarcinoma (1 paper); Blindness (1); breast carcinoma (1); cataract (1); cholesteatoma (1); metabolic disorders (1); oligospermia (1); retinoblastoma (1); teratospermia (1).